ARID1B (AT-rich interaction domain 1B)
Diseases named in the same sentence as ARID1B in open-access papers (continued):
Sharing a sentence is not in itself a finding about the gene and the disease.
breast carcinoma (16 papers, 2014 to 2025). "Although our study establishes a compelling rationale for targeting ARID1B as a therapeutic vulnerability in ARID1A‐deficient breast cancers, further preclinical validation is warranted." (PMID 40671262, 2025). "ARID1B also acts as a prognostic biomarker whose expression is associated with disease-free survival in breast cancer patients." (PMID 41278204, 2025). "Consistent with previous reports, we observed that high mRNA and protein levels of ARID1B are associated with a worse breast cancer prognosis." (PMID 40671262, 2025). "Various evidence illustrates that inactivating mutations in ARID1B enable the clonal selective advantage in cancer cells, especially in breast cancer with drug relapse." (PMID 41278204, 2025). "In summary, developing inhibitors to specifically target ARID1B nuclear translocation shows promise for a more precise therapeutic approach in breast cancer, aiming to reduce off‐target effects linked with broader chromatin remodeling inhibitors." (PMID 40671262, 2025). "In breast cancer, ARID1B is identified as one of the driver mutations that give cancer cells a clonal selective advantage." (PMID 38365747, 2024). "ARID1A and ARID1B in the BAF subfamily are frequently mutated in breast cancer." (PMID 41278204, 2025). "Similarly, in breast cancer, ARID1B overexpression was associated with worse outcomes via disruption in the SWI/SNF complex." (PMID 40806597, 2025). "Here, ARID1B mRNA expression was associated with poor prognosis in HER2-riched breast cancers and lymph node-positive patients, ARID4B mRNA expression, which was higher in breast cancer tissues, was interrelated with unfavorable prognosis in all breast cancer patients." (PMID 33592583, 2021). "Additionally, high levels of ARID1B expression have been linked to poor clinical outcomes in bladder urothelial carcinoma and breast carcinoma, while low ARID1A levels have been linked to poor clinical outcomes." (PMID 31796878, 2019). "In addition, analysis has shown that the level of ARID1B expression is associated with the disease-free survival of breast cancer patients, and that the 5-year survival rate of ARID1B-positive patients is significantly lower than that of ARID1B-negative patients." (PMID 38365747, 2024). "To decipher the impact of ARID1B cellular protein abundance in tumor malignancy, we examined the expression of ARID1B in a panel of breast cancer cell lines, including mammary gland epithelial, luminal, HER2+ and TNBC." (PMID 40671262, 2025). "In this study, we elucidate the role of ARID1B in breast tumorigenesis and therapy by analyzing publicly available datasets from breast cancer patients, human specimens, conducting in vitro experiments, and utilizing animal models." (PMID 40671262, 2025). "To further clarify the extent to which IPZ‐ and BRMi‐induced transcriptional changes are ARID1B‐dependent, we performed an in‐depth comparison with ARID1B expression‐dependent transcriptomes in breast cancer patients." (PMID 40671262, 2025). "To assess the functional implications, we conducted rescue experiments using a colony formation assay in breast cancer cells with ARID1B KO background." (PMID 40671262, 2025). "In this study, using a multidisciplinary approach that included clinical cohorts of human breast cancer patients, we dissected the role of ARID1B in breast tumor progression and drug resistance." (PMID 40671262, 2025). "Using patient sample data obtained from the Clinical Proteomic Tumor Analysis Consortium (CPTAC), we compared ARID1B protein levels between normal and tumor tissues amongst ten different types of cancer, including breast cancer." (PMID 40671262, 2025). "To further determine the relevance of aberrant accumulation in tumor development, we either overexpressed (OE) or depleted (KO) ARID1B in breast cancer cells and evaluated its impact on cancer cell growth." (PMID 40671262, 2025).
breast carcinoma (continued). "We identified components of a cytonuclear transport system, including importins KPNA2 and KPNB1, as well as a subunit of the NPC RANBP2, as binding partners of ARID1B in breast cancer cells." (PMID 40671262, 2025). "The accumulation of ARID1B in aggressive breast cancer subtypes such as TNBC attracts our attention because of its aggressive malignant feature with a lack of suitable therapeutic options." (PMID 40671262, 2025). "Since ARID1B protein expression positively correlates with stemness‐related proteins in breast cancer patients, we further investigated the role of ARID1B OE in the cancer stem cell maintenance using 3D mammosphere formation assay." (PMID 40671262, 2025). "Our analysis showed that ARID1B protein levels were significantly higher in breast cancer and glioblastoma compared to normal tissue." (PMID 40671262, 2025). "Elevated expression of ARID1B significantly decreased ARID1A levels in multiple breast cancer cell lines at both the protein and mRNA levels." (PMID 40671262, 2025). "On the other hand, ARID1B is highly expressed in TNBC compared to other molecular types of breast cancer." (PMID 41278204, 2025). "We identified 49 genes (10.6%) concurrently upregulated and 168 genes (20.1%) concurrently downregulated in ARID1A‐mutant and ARID1B‐high breast cancer samples." (PMID 40671262, 2025). "Current research also indicates that ARID1B is highly expressed in triple-negative breast cancer subtypes compared to other molecular subtypes of breast cancer." (PMID 38365747, 2024). "Depletion of ARID1B also disrupts the stability of the SWI/SNF complex and inhibits the proliferation of ARID1A-deficient breast cancer." (PMID 38365747, 2024). "Univariate statistical analysis showed that high expression of ARID1B is closely related to the age of breast cancer patients, tumor size, histological tumor grade, and nuclear polymorphism." (PMID 38365747, 2024). "Other gene knockouts (RUNX1, CDH1, and ARID1B) have similar effect, consistent with their reported tumor-suppressor roles in breast cancer or other cancer types." (PMID 31980032, 2020). "Examples include mutations in the ARID1A gene occurring in a subset of ovarian cancers and breast cancers along with mutations in the MLL2, MLL3, SMARCD1, NCOR1 and ARID1B genes found in a subset of breast cancers." (PMID 25468711, 2015). "The low levels of ARID1A observed in breast cancer may be attributed to ARID1B higher affinity for the BAF core, increased ARID1A degradation, or both." (PMID 40671262, 2025). "To test this hypothesis, we conducted bioinformatic analyses comparing transcriptional profiles of ARID1B‐high versus ARID1B‐low breast cancer samples." (PMID 40671262, 2025). "Additionally, we performed single‐sample gene set enrichment analysis (ssGSEA) to evaluate enrichment scores for cell proliferation‐related pathways and cancer progenitor cell‐related pathways in breast cancer patients grouped by ARID1B expression levels." (PMID 40671262, 2025). "The marked increase in ARID1B expression in breast tumor tissues implies that ARID1B may be a promising therapeutic target for breast cancer." (PMID 40671262, 2025). "This potential upregulation of ARID1B raises important questions about its function in breast cancer progression and whether it acts as an adaptive mechanism or contributes to oncogenesis." (PMID 40671262, 2025). "We next investigated whether ARID1B accumulation in breast cancer affects the efficacy of current targeted therapy regimens." (PMID 40671262, 2025). "ARID1A and ARID1B may influence breast cancer by promoting various cellular functions related to tumor suppression, hence controlling aggressiveness and therapeutic response." (PMID 41278204, 2025). "Moreover, the elevated ARID1B protein expression was detected in different molecular subtypes of breast cancer, including luminal, HER2+, and TNBC, compared to normal breast tissue." (PMID 40671262, 2025).
breast carcinoma (continued). "Additionally, immunohistochemistry (IHC) analysis of breast cancer patient specimens confirmed the high levels of ARID1B in cancerous tissues." (PMID 40671262, 2025). "In summary, ARID1B may be a prognostic and predictive biomarker for breast cancer and an effective therapeutic target for its treatment." (PMID 38365747, 2024). "Interestingly, this deletion also strikes ARID1B, a new tumor suppressor gene found in breast cancer." (PMID 26554380, 2015). "Some studied showed that increased expression of ARID1B forebodes poor survival in triple-negative breast cancer patients, while, another one reported ARID1B potentially served as a valuable prognostic indicator and therapeutic target in breast cancer patients with triple-negative subtypes." (PMID 33592583, 2021). "Next, we examined differentially expressed genes (DEGs) between ARID1A‐mutant and ARID1A‐wildtype (WT) breast cancer samples to understand the transcriptional interplay between ARID1A and ARID1B." (PMID 40671262, 2025). "Therefore, high expression of ARID1B may contribute to the occurrence of breast cancer." (PMID 38365747, 2024). "The mRNA expression of ARID1B (p=0.0375), ARID4B (p=0.0086), JARID1B (p=0.0003) and JARID1D (p=0.0138) were interrelated with worse survival in breast cancer patients with positive lymph node." (PMID 33592583, 2021). "So the effect of ARID1B and ARID4B in breast cancer served as oncogenes in the previous and present study." (PMID 33592583, 2021). "Several cancer-associated chromatin remodeling factors other than BAF155 have already been identified in breast cancer; for example, ARID1A, ARID1B, SMARCD1, PBRM1, BAF60A and BRG1." (PMID 25927994, 2014). "IPZ treatment for 2 h resulted in a significant reduction in nuclear ARID1B levels without affecting total ARID1B abundance and led to suppression of breast cancer cell growth." (PMID 40671262, 2025). "We observed a significant upregulation of ARID1B in all types of breast cancer cells when compared to the normal breast epithelial (184‐B5) or non‐tumorigenic breast epithelial cell lines (MCF10A and MCF12A)." (PMID 40671262, 2025). "IHC analysis of ARID1A levels in breast cancer samples showed a negative correlation between ARID1B and ARID1A." (PMID 40671262, 2025). "Moreover, among the tested ER+ breast cancer cells, ARID1A mutant T47D cells had higher ARID1B mRNA and protein levels compared to those of ARID1A WT cells." (PMID 40671262, 2025). "Interestingly, some breast cancer samples also displayed a strong ARID1B signal in the cytoplasm, while others did not, suggesting dysregulation of ARID1B and its nuclear import mechanisms." (PMID 40671262, 2025). "For the non-cancer adipose-breast network that we applied to the breast cancer GWAS, Downstreamer prioritised seven known breast cancer driver genes among the top 100 genes: CREBBP, TRPS1, ARID1A, ARID1B, XBP1, SPEN and NUMA1." (PMID 39010058, 2024). "The expression of ARID1A, ARID1B, ARID2, ARID3A, ARID4A, and ARID4B in no-luminal subtypes was lower than luminal subtypes, however, ARID3C, ARID5A, and JARID2 mRNA expression were higher in no-luminal subtypes of breast cancer tissues." (PMID 33592583, 2021). "The low mRNA expression of ARID1B (p=0.0023), ARID2 (p=0.0439), ARID4A (p=0.0056), ARID4B (p=0.0317), ARID5B (p=0.00054), JARID1D (p=0.043), JARID2 (p=0.0068) were interrelated with poor survival in breast cancer patients with negative lymph node." (PMID 33592583, 2021).
autism (15 papers, 2012 to 2025). Persistent deficits in social interaction and communication and interaction as well as a markedly restricted repertoire of activity and interest as well as repetitive patterns of behavior. "ARID1B is involved in GABA neuron development, and mice deficient in ARID1B serve as a model of autism." (PMID 40725218, 2025). "In mice, sevoflurane exposure induced autism-like behaviours and led to the downregulation of high-risk autism genes, including ARID1B, GABRA5, GABRB3, GRIN2B, SHANK3 and SUV420H1." (PMID 39372140, 2024). "Arid1b and Chd8 are two of the most frequently mutated genes in autism patients, encode chromatin remodelers, and are widely expressed in many cell types—including granule cells—of the developing and adult cerebellum." (PMID 36865235, 2023). "In the current study, a dual-luciferase reporter assay confirmed miR-873 variants have a 20-30% inhibition/dysregulation effect on candidate autism risk genes ARID1B, SHANK3 and NRXN2 and also confirmed the affected expression with qPCR." (PMID 33262327, 2020). "Autism risk genes, ARID1B, SHANK3 and NRXN2 were specially of interst, using a dual-luciferase assay we confirmed the direct targeting of MRE of SHANK3 by miR-873 albeit, WT and Mut miR-873 mimics similarly dysregulate Renilla luciferase." (PMID 33262327, 2020). "Recent studies compared the probability of recurrent de novo mutation in individual genes among autism probands, and found ARID1B to be the second most likely gene to carry a de novo mutation in a patient with autism." (PMID 30123105, 2018). "Haploinsufficiency of ARID1B was reported to cause corpus callosum abnormalities, ID, speech impairment and autism, suggesting the ARID1B LoF is causative and sufficient in this case." (PMID 28539120, 2017). "In conclusion, large genetic studies in autism cohorts have identified ARID1B and other genes involved in chromatin remodeling to be frequently mutated in children with ASD." (PMID 30123105, 2018). "The association between autism and SSRIDD is supported by a recently published Arid1b mouse model, which demonstrated autism-like behaviors in Arid1b-haploinsufficient mice." (PMID 30123105, 2018). "De novo deletion of ARID1B in autism may be related to the pathogenesis of autism." (PMID 32824515, 2020).
autism spectrum disorder (11 papers, 2015 to 2025). A spectrum of developmental disorders that includes autism, and Asperger syndrome. "Mutations in ARID1A are associated with craniofacial abnormalities, while mutations in ARID1B are associated with autism spectrum disorder and SCZ." (PMID 35444632, 2022). "ARID1B, a chromatin remodeler implicated in neurodevelopmental disorders, including autism spectrum disorder, exhibits strong embryonic- and early postnatal-stage expression." (PMID 36030255, 2022). "AT-rich interactive domain 1B (ARID1B), a chromatin modifier, has been linked to autism spectrum disorder and to affect rare and inherited genetic variation in a broad set of NDDs." (PMID 33757588, 2021). "ARID1B, a chromatin remodeler, is strongly implicated in autism spectrum disorders (ASD)." (PMID 38516548, 2023). "ARID1B is a chromatin remodeler associated with autism spectrum disorders." (PMID 36030255, 2022). "In addition, ARID1B is among the most frequently mutated genes in autism spectrum disorders (ASD) and non-syndromic ID." (PMID 28695822, 2017). "ARID1B de novo mutations have been shown to contribute to the heritable complex traits, such as autism spectrum disorders (ASDs), although the effect size may be small." (PMID 26376624, 2015).
BAFopathy (11 papers, 2021 to 2024). Disorder caused by mutations in the various subunits composing the BAF complex. "Transcriptome and methylation analysis revealed a transcription profile similar to that of ARID1B haploinsufficiency variants and a BAFopathy episignature, respectively." (PMID 39028335, 2024). "The photograph of this patient clustered with ARID1B patients, his DNA methylation pattern was compatible with a BAFopathy and this variant was considered pathogenic." (PMID 34440449, 2021). "The ARID1B-associated BAFopathy belongs to the mild CSS spectrum." (PMID 39028335, 2024). "Studies have shown that DNAm profiles at subsets of CpGs overlap between individuals with BAFopathies carrying variants in SMARCA2 that cause NCBRS, and in ARID1B, SMARCB1, and SMARCA4 that lead to Coffin-Siris syndromes type 1, 3, and 4, respectively." (PMID 35361921, 2022). "Typical CSS, which is also referred to as BAFopathy, is caused by variants in the subunit of BAF complex, including ARID1A (OMIM#603024), ARID1B (OMIM#614556), SMARCA4 (OMIM#603254), SMARCB1 (OMIM#601607), ARID2 (OMIM#609539), and SMARCE1 (OMIM#603111)." (PMID 35938035, 2022). "Among the most prominent and most studied BAFopathies are the clinically overlapping syndromes CSS and Nicolaides-Baraitser (NCBRS) (MIM: 601358), caused by variants in BAF complex proteins: ARID1B in CSS1, SMARCB1 in CSS2, and SMARCA4 in CSS4; and SMARCA2 in NCBRS." (PMID 38751117, 2024). "Other combined episignatures, such as for the BAFopathy (genes: ARID1A, ARID1B, SMARCB1, SMARCA2 and SMARCA4) episignature, are already proving their clinical utility." (PMID 38787418, 2024). "We detected a predominantly hypermethylation profile; the highest percentage of overlap in DMPs was with BAFopathies (11%, including ARID1A, ARID1B, SMARCB1, SMARCA2, SMARCA4), and CHARGE syndrome (10%, CHD7)." (PMID 38351292, 2024). "BAFopathy presented with a ~4% overlap, including ARID1A, ARID1B, SMARCB1, SMARCA2, and SMARCA4, and includes several neurodevelopmental disorders caused by variants in genes within the BRG1/BRM-associated factor (BAF) complex." (PMID 37762546, 2023). "This analysis showed that TRIP12 is most closely related to the CSS9 (SOX11), BAFopathy (ARID1A, ARID1B, SMARCB1, SMARCA2, SMARCA4) and MRD23 (SETD5) episignatures." (PMID 36430143, 2022). "Notably, JARID2 exhibited the highest overlap with CHARGE (~7%, CHD7), BAFopathy (~4%, including ARID1A, ARID1B, SMARCB1, SMARCA2, SMARCA4), and the PCR2 complex, which houses Cohen–Gibson syndrome (COGIS) and Weaver syndrome (WVS) (~4%, EED, EZH2)." (PMID 37762546, 2023). "His photograph clusters with other ARID1B patients, but the methylation pattern in his blood was not compatible with a BAFopathy." (PMID 34440449, 2021). "Similarly, the DNA methylation result of Case 1 is not compatible with a BAFopathy, whilst his photograph clusters with ARID1B patients and his phenotype may fit within the ARID1B spectrum." (PMID 34440449, 2021).